ALB (albumin)
Diseases named in the same sentence as ALB in open-access papers (continued):
Sharing a sentence is not in itself a finding about the gene and the disease.
pneumonia (continued). "In our study, although multivariate analysis did not reveal a significant association, univariate descriptive analysis demonstrated that admission albumin levels were lower in the patient group with pneumonia compared to those without pneumonia." (PMID 39857079, 2025). "This cohort study investigated the associations between serum albumin and gamma gap levels, and their combined effect, and risk of deaths from all-causes, cancer, CVD, RSD without pneumonia, pneumonia, and other-causes in a Japanese population." (PMID 41248155, 2025). "A non-linear dose–response relationship between preoperative albumin levels and postoperative pneumonia was observed using a restricted cubic spline model." (PMID 41200138, 2025). "The present study showed that elevated serum gamma gap levels with medium albumin levels were independently associated with increased HRs for deaths of all-causes, CVD, and RSD without pneumonia, after adjusting for related factors." (PMID 41248155, 2025). "The correlation between white blood cells, percentage, C-reactive protein, and pneumonia was stronger, while albumin showed a negative correlation with pneumonia." (PMID 39398953, 2024). "The severe pneumonia group also had significantly lower hemoglobin, platelet count, albumin, oxygen saturation, pH, and bicarbonate than the non-severe pneumonia group." (PMID 38887257, 2024). "The preoperative albumin levels of patients with postoperative pneumonia were significantly different (p = 0.03) than those of patients without postoperative pneumonia." (PMID 37232788, 2023). "Our study found that being of age > 85 years, of the male sex, having pneumonia, pressure ulcers, CCI ≥ 8, functional dependency for four or more ADLs, dysphagia, abnormal urea, and abnormal albumin were predictive of one-year mortality among patients with AD in the acute care setting." (PMID 37118683, 2023). "Such an intervention not only reduced the number of pneumonia cases, but also improved other nutritional statuses (serum total protein and albumin levels) without the administration of albumin products." (PMID 36142971, 2022). "For these reasons, nutritional assessments using only albumin, prealbumin, or transthyretin are not appropriate for dysphagia patients who are prone to acute inflammation such as pneumonia." (PMID 33673581, 2021). "Additionally, all patients with low albumin and high CRP levels developed pneumonia initially or subsequently, even with the administration of effective antimicrobials, and subsequently died." (PMID 28938875, 2017). "Following S. pneumoniae lung infection by i.n. inoculation of 5x106 CFU of TIGR4, human IgG concentrations increased in BALF over time and correlated with BALF murine albumin levels, a marker of serum leak into alveolar spaces." (PMID 28135322, 2017). "However, evidence regarding the relationship between preoperative albumin levels and postoperative pneumonia in major non-cardiac surgeries remains limited." (PMID 41200138, 2025). "Especially, particular attention may be given to people with low albumin and high gamma gap for RSD without pneumonia, and low albumin and low gamma gap for pneumonia." (PMID 41248155, 2025). "To assess whether the connection between AST/ALT and 28-day all-cause mortality might differ in various contexts, we executed a subgroup analysis focusing on age, gender, ethnicity, respiratory rate, heart rate, MAP, AMI, pneumonia, GCS score, creatinine, albumin, WBC, hemoglobin." (PMID 40670661, 2025). "On the other hand, a meta-analysis conducted in 2020 showed no notable distinction in body mass index (BMI), serum albumin level, wound infections, or pneumonia among postoperative GI cancer patients who were administered enteral nutritional therapy that included ω-3 FAs." (PMID 37686570, 2023).
pneumonia (continued). "SMART-COP (systolic blood pressure, multilobar infiltrates, albumin, respiratory rate, tachycardia, confusion, oxygen, and pH) is a severity score method designed to identify individuals who require intensive respiratory or vasopressor support (IRVS) support due to pneumonia." (PMID 36043007, 2022). "Of note, respiratory rate, blood pressure, pulse, haemoglobin, c-reactive protein (CRP), prothrombin time (PT), activated partial thromboplastin time (APTT), and albumin were found to have significant differences between the patients with or without pneumonia (P < 0.05)." (PMID 36684357, 2022). "Patients with COVID-19 pneumonia were older, had a higher BMI, more likely to have comorbidity, more likely to have symptom, such as fever, cough, dyspnea and desaturation, lymphocytopenia, higher C-reactive protein (CRP), lower albumin, and higher globulin than those without pneumonia." (PMID 33902480, 2021). "BMI and serum albumin concentration in the AP and CAP groups were significantly lower than those in the Con group, suggesting that improving nutrition status may have a beneficial effect on pneumonia." (PMID 31477059, 2019). "On multivariate analysis, independent predictors of pneumonia occurrence in CAPD patients with DN were high body mass index (hazard ratio [HR], 1.15; 95% confidence interval [CI], 1.01–1.31; P = 0.037) and low serum albumin level (HR, 0.87; 95% CI, 0.78–0.98; P = 0.014)." (PMID 23585903, 2013). "The increased HRs with high gamma gap levels were higher in low albumin group than in medium albumin group, particularly for RSD without pneumonia." (PMID 41248155, 2025). "Findings of the present study also suggest that the examination of some variables, such as serum albumin, PaO2, and pH, which might not be universally available for real-time clinical decision-making, might still be worthwhile to assess at the time of pneumonia diagnosis to improve patient care." (PMID 35022026, 2022). "The probabilities of developing pneumonia in patients with or without high CRP and low albumin levels were 100% (9/9) and 10.5% (4/38), respectively (p < 0.01)." (PMID 28938875, 2017). "This may reflect pneumonia severity, or the large proportion of PLWH, the majority of whom were not on ART, as albumin levels in PLWH are lower pre-ART and correspond with weight and CD4 cell count." (PMID 40665761, 2025). "Notably, hepatic malignancy, hematocrit (HCT), alanine transaminase (ALT), total bilirubin (TBIL), albumin (ALB), coagulation function, MELD score, and hospital stay were found to have significant differences between patients with or without postoperative pneumonia (P < 0.05)." (PMID 33789673, 2021).
liver fibrosis (293 papers, 2005 to 2026). "We conclude that PR‐PFD demonstrated statistically significant efficacy in reducing noninvasive markers of liver fibrosis and improving biological tests associated with liver function (albumin, bilirubin, Child–Pugh, and MELD scores)." (PMID 40402087, 2025). "CD4+ counts, albumin, direct bilirubin, and indirect bilirubin were associated with liver fibrosis, probably due to sociodemographic factors such as social stratum, level of education, and late diagnosis of HCV." (PMID 39599839, 2024). "The results indicated that age, AST, AST/ALT ratio, albumin, triglycerides, and platelet count were independent risk factors for advanced hepatic fibrosis in the T2DM group." (PMID 39594165, 2024). "Transaminases, albumin, and prothrombin time were closely related to the degree of liver inflammation, while liver stiffness was associated with liver fibrosis, inflammation, and portal pressure." (PMID 38627672, 2024). "Abnormal liver function tests and markers of liver fibrosis are associated with poor prognoses in HF, such as reduced albumin(ALB) and increased bilirubin and transaminases." (PMID 37794360, 2023). "The analysis demonstrated that increased TBK1 expression was associated with higher degree of platelet-to-albumin ratio, liver fibrosis and tumor stage." (PMID 33679751, 2021). "Based on the pocket-escaping NIR fluorophore, a novel probe was developed that successfully prevented the interference of unspecific signal caused by albumin in the imaging of liver fibrosis in a mouse model." (PMID 32218438, 2020). "The liver synthesizes albumin, and when the chronic liver injury causes liver fibrosis, albumin decreases." (PMID 29887908, 2018). "Multiple analysis showed C5a, AST, laminin, Co-IV, platelet count, albumin, HBsAg associated with liver fibrosis independently." (PMID 27605044, 2017). "Platelet count and serum albumin level, which decreased in association with the progression of hepatic fibrosis, were associated with serum WFA+-M2BP level as well." (PMID 27999409, 2016). "It is likely that liver fibrosis, accompanied by the damage of liver regeneration, could cause a reduction in normal hepatocytes, finally resulting in lower ALB levels." (PMID 39949770, 2025). "CD4+ counts, albumin, direct bilirubin, and indirect bilirubin were associated with liver fibrosis." (PMID 38787212, 2024). "Another parameter associated with liver fibrosis was low albumin levels." (PMID 38787212, 2024). "Cefotaxime also caused a notable decrease in serum albumin levels, which may be attributed to liver fibrosis." (PMID 39698236, 2024). "To determine whether FGF18 attenuates or exacerbates liver fibrosis in CflarLKO mice, we generated hepatocyte-specific Fgf18-deficient mice (Fgf18LKO mice) by crossing albumin-Cre mice with Fgf18FF mice." (PMID 37813881, 2023). "Based on the pocket-escaping NIR fluorophore, a novel probe was developed that successfully prevented the interference of unspecific signal caused by albumin in the detection of liver fibrosis in a mouse model, while the control probe developed based on conventional strategy failed." (PMID 32218438, 2020). "Therefore, our results need to be interpreted with caution and further study in large population is necessary to explore whether there is significant association between serum albumin and depression in each stage of liver fibrosis." (PMID 34983435, 2022). "Age, PCIII, CIV, LN, HA, PLT count, TB, DB, ALT, AST, GGT, ALP, ALB, and γ-globulin levels differ among the four stages of liver fibrosis." (PMID 41601755, 2026). "Hepatic inflammation was assessed using serum ALT levels, hepatic function was evaluated with the albumin–bilirubin score, and hepatic fibrosis was estimated using Mac-2 binding protein glycosylation isomer (M2BPGi) levels." (PMID 39997725, 2025).
liver fibrosis (continued). "Coriobacteriaceae_UCG-002, Desulfovibrio, and [Eubacterium]_brachy_group were positively correlated with AST levels, liver fibrosis, liver coefficient, and inflammation and negatively correlated with ZO-1 and ALB levels." (PMID 40552147, 2025). "The ATA score was developed using three key laboratory parameters that are closely associated with liver fibrosis: AST, platelet count, and serum albumin." (PMID 40361937, 2025). "Mn@Albumin nanoparticles: Senescence of activated HSCs and related impaired immune clearance are crucial for the progression of hepatic fibrosis." (PMID 39665319, 2025). "We established hepatocyte-specific Men1-KO mice (albumin-cre; Men1f/f, Men1ΔH/ΔH), and a liver fibrosis model was established by treating mice with CCL4." (PMID 40651612, 2025). "The neutrophil percentage-to-albumin ratio (NPAR), a novel inflammatory indicator, is significantly associated with NPAR and risk of NAFLD and advanced liver fibrosis." (PMID 40547368, 2025). "Basic research has confirmed that ALB interacts with the VA metabolic pathway, playing a crucial role in liver fibrosis development." (PMID 40843069, 2025). "ALB is mainly produced by hepatocytes, and the decrease of ALB reflects the poor basal nutritional status of patients with CHB-related liver fibrosis." (PMID 39286781, 2024). "In laboratory tests, our results indicated that ALB and GLB were important predictors for the diagnosis of CHB-associated advanced liver fibrosis." (PMID 39286781, 2024). "This study aimed to investigate the effect of phenylethanol glycoside from Cistanche tubulosa (CPhGs) on the prevention of bovine serum albumin (BSA)-induced hepatic fibrosis in rats." (PMID 39338312, 2024). "Elevated circulating concentrations of ALT, AST, ALP and TBIL, accompanied by diminished ALB levels, were characterized in the liver fibrosis rat model." (PMID 38874773, 2024). "Although each trial showed an increase in ALB levels after MSCs treatment for liver fibrosis, there was significant heterogeneity [p < 0.00001, I2 = 86%; SMD = −2.90, 95% CI (−3.70, −2.11), p < 0.00001]." (PMID 39104627, 2024). "An additional connection between increased NFS and advanced hepatic fibrosis is that the latter is substantially correlated with abnormalities in AST, ALT, platelets, and albumin, which are closely linked to advanced hepatic illness." (PMID 39179677, 2024). "The results showed that curcumin can reduce the levels of ALT, AST, ALP, TBIL, bax protein and index of liver in hepatic fibrosis models, and improve the levels of ALB and A/G of the hepatic fibrosis models." (PMID 38781262, 2024). "An analysis based on NHANES 2017–2018 showed that the neutrophil-to-albumin ratio (NPAR), a systemic marker of inflammation, was significantly associated with NAFLD and advanced liver fibrosis." (PMID 39882525, 2024). "The identified factors were age (≥40 years), the presence of MASLD, advanced liver fibrosis, levels of ALB, ALP, and HDL cholesterol, HBV DNA concentration ≥6 log10 IU/mL, and HBeAg positivity." (PMID 38405121, 2024). "A total of 20 trials from 18 studies reported differences in the serum ALB concentration between the experimental groups and control groups of MSCs for liver fibrosis." (PMID 39104627, 2024). "In fact, AST, ALT, albumin and platelet count have been incorporated into several established scores for noninvasive assessment of liver fibrosis (e.g., FIB-4, APRI, and non-alcoholic fatty liver disease fibrosis score (NFS))." (PMID 39666107, 2024). "The degree of liver fibrosis increased with decreased albumin, alanine aminotransferase and platelet count levels, and increasing age." (PMID 39470560, 2024). "Despite the bovine serum albumin (BSA)-induced liver fibrosis model being an excellent immunological hepatic fibrosis model, it has not received much attention from the researchers worldwide." (PMID 37781475, 2023).
liver fibrosis (continued). "Especially in immunological hepatic fibrosis, the bovine serum albumin (BSA)-induced liver fibrosis models have the same developmental mechanisms as human liver fibrosis models, but have received little attention." (PMID 37781475, 2023). "Whereas transgenic expression of PDGFB in the liver under albumin promoter increased collagen deposition and promoted CCl4-induced liver fibrosis, ablation of PDGFRβ in HSCs attenuated liver fibrosis." (PMID 37860002, 2023). "In summary, our study showed anti-Schistosoma IgG and elevated Albumin/Globulin and GGT levels were independently associated with liver fibrosis reticular changes in patients with chronic schistosomiasis japonica." (PMID 37580417, 2023). "Our study included 488 patients and logistic regression analysis showed that globulin, albumin/globulin, GGT levels and anti-Schistosoma IgG were independently associated with liver fibrosis in patients with schistosomiasis." (PMID 37580417, 2023). "The FIB-4 index as a surrogate marker of liver fibrosis, serum albumin level, PT (%) as a marker of liver function, and the AFP level were measured at baseline, EOT, and SVR12 in all analyzed patients." (PMID 37268672, 2023). "Patients with liver fibrosis have damaged liver cells, reduced liver function, and reduced ability to synthesize albumin." (PMID 35668948, 2022). "In the HCV-infected group, the serum levels of ALB, Dbil, HA and Tbil in patients with liver fibrosis were significantly different from those in patients with hepatitis (P < 0.05)." (PMID 35646962, 2022). "HGF derived from MSCs can also accelerate HSCs apoptosis, and MSCs cultured with HGF can improve serum albumin level, reducing liver fibrosis." (PMID 35663940, 2022). "Third, classical predictors of HCC such as advanced liver fibrosis, and platelets count and albumin in cirrhotic patients were found." (PMID 35566592, 2022). "In contrast, the serum level of ALB was significantly reduced in the hepatic fibrosis group, which was reversed by BMSC treatment." (PMID 35902883, 2022). "Serum albumin is closely related with liver fibrosis and the albumin platelet product has been validated in liver fibrosis staging." (PMID 34983435, 2022). "While promoting liver cell repair and regeneration, it can also reduce liver fibrosis, regulate the imbalance of amino acid levels, and form a virtuous cycle, which is beneficial to the synthesis of albumin in the body and has few adverse reactions." (PMID 35251204, 2022). "Based on Fuc-Hp levels at EOT, BMI, and albumin levels at EOT, we were able to stratify the risk of HCC occurrence after SVR among patients with advanced liver fibrosis." (PMID 36542633, 2022). "ALB has been confirmed as an independent indicator of advanced liver fibrosis in patients with NAFLD, and it can also significantly contribute to the index for staging liver fibrosis in patients with viral hepatitis." (PMID 35347597, 2022). "Liver fibrosis and the platelet-to-albumin ratio are important indicators of liver inflammation, which results in impaired antitumor immune response." (PMID 33679751, 2021). "The intrasplenic transplantation of SHED-Heps into CCl4-treated mice showed that donor SHED-Heps behaved as human hepatocyte paraffin 1- and human albumin-expressing hepatocyte-like cells in situ and ameliorated CCl4-induced liver fibrosis." (PMID 33436050, 2021). "In the current study, the changes in platelet count after DAA therapy were negatively correlated with baseline PV diameter, stage of hepatic fibrosis, and serum total bilirubin and positively correlated with baseline serum albumin." (PMID 34122539, 2021). "Pdgfc-Tg mice express Pdgfc under the control of the albumin promoter and develop hepatic fibrosis and HCC7." (PMID 34158541, 2021). "In the present study, the INPR significantly increased as the liver fibrosis stage increased, while hepatic function, such as cholinesterase, albumin, and prealbumin, significantly decreased as liver fibrosis progressed." (PMID 33526976, 2021).